DSP (desmoplakin)
Diseases named in the same sentence as DSP in open-access papers (continued):
Sharing a sentence is not in itself a finding about the gene and the disease.
lymph node metastasis (1 paper, 2021). "DSP is downregulated in human OSCC, and the decrease in DSP staining is associated with loss of differentiation, degree of invasion, and the presence of lymph node metastasis." (PMID 34203070, 2021).
lymphoma (1 paper, 2013). A malignant (clonal) proliferation of B- lymphocytes or T- lymphocytes which involves the lymph nodes, bone marrow and/or extranodal sites. "The DNA methylation biomarker panel consisting of DSP, FZD8, KCNH2, and PPP1R14A was positive in 89% (54/61) of all lymphomas." (PMID 24260260, 2013). "However, this is, to the best of our knowledge, the first time DSP, FZD8, KCNH2, MTSS1, and PPP1R14A have been reported to be methylated in lymphoma." (PMID 24260260, 2013).
memory impairment (1 paper, 2021). "In addition, DSP-4 treatment attenuated hippocampal-dependent learning and memory impairment in rats with POCD, with a downregulation of the activation of microglia and astrocytes in the prefrontal cortex and hippocampus." (PMID 34916906, 2021).
myofibrillar myopathy (1 paper, 2025). "Truncating variants in TTN are strongly associated with DCM, while mutations in DSP, LMNA, MYH7, RBM20, TNNT2, BAG3, and FLNC (the latter being linked to myofibrillar myopathy) are also commonly implicated." (PMID 39857686, 2025).
pancreatic disease (1 paper, 2021). "Other studies revealed an association between pancreatic disease and allelic variants of the EPHX1 (epoxide hydrolase 1), DSP (desmoplakin), HLA-DQA1, and HLA-DQB1 (major histocompatibility complex) genes." (PMID 34945117, 2021).
paraneoplastic pemphigus (1 paper, 2018). Pemphigus is a group of chronic autoimmune skin diseases characterized by blisters formation on the outer layer of the skin and the mucous membranes. "A cumulative autoimmune response to periplakin, envoplakin, BPAG1, and desmoplakin has been described in persons affected by paraneoplastic pemphigus that results in a dismal prognosis with a 75–90% mortality rate and a mean survival < 1 year." (PMID 29373494, 2018).
Parkinson disease (1 paper, 2013). A progressive degenerative disorder of the central nervous system characterized by loss of dopamine producing neurons in the substantia nigra and the presence of Lewy bodies in the substantia nigra and locus coeruleus. "Our next step was to test the DSP/βME treatment on the αSyn protein source most relevant to the study of Parkinson’s disease, human brain (left two lanes labled ‘H.s.’)." (PMID 24278419, 2013).
pemphigus (1 paper, 2023). Pemphigus is a group of rare autoimmune diseases that cause blistering of the skin and mucous membranes (mouth, nose, throat, eyes, and genitals).This conditioncan occur at any age, but often strikes people in middle or older age. "In these conditions, acantholysis is due to direct disruption of desmosomes, either through the production of autoantibodies against Dsg1 in pemphigus or mutations in Dsg1 or desmoplakin in SAM syndrome." (PMID 37471166, 2023).
pneumoconiosis (1 paper, 2025). An occupational lung disorder caused by inhalation of dust particles. "Currently, genome-wide association studies (GWAS) have identified a strong association between some common single-nucleotide polymorphisms (SNPs), such as small nucleolar RNA host gene 14 (SNHG14), desmoplakin (DSP), and laminin beta 1 (LAMB1), and pneumoconiosis." (PMID 40182855, 2025).
pterygium (1 paper, 2021). A wedge-shaped fibrovascular lesion arising from the bulbar conjunctiva and extending to the cornea. "After analyzing the differentially methylated m6A peaks and synchronously differentially expressed genes, we searched the Gene Expression Omnibus database and identified five genes related to the development of pterygium (DSP, MXRA5, ARHGAP35, TMEM43, and OLFML2A)." (PMID 34249924, 2021). "Using GEO databases, we also identified five hub genes (DSP, MXRA5, ARHGAP35, TMEM43, and OLFML2A) that were most correlated with the development of pterygium." (PMID 34249924, 2021).
schizophrenia (1 paper, 2023). A major psychotic disorder characterized by abnormalities in the perception or expression of reality. "Consequently, DSP has been associated with treatment resistance in schizophrenia, and some important publications on this theme were identified by this study." (PMID 37333928, 2023).
scleroderma (1 paper, 2022). Scleroderma is a rare autoimmune connective tissue disorder characterized by abnormal hardening of the skin and, sometimes, other organs. "However, mesenchymal–epithelial transition (MET) associated proteins such as SCRIB, DSP, TJP1, CDH1, DLG1, and TJP2 were downregulated in scleroderma skin, indicating the high severity of skin fibrosis in mice with scleroderma." (PMID 35315234, 2022).
scrapie (1 paper, 2010). A fatal disease of the nervous system in sheep and goats, characterized by pruritus, debility, and locomotor incoordination. "In contrast, in vitro amplification of sheep scrapie PrPSc was completely inhibited by the addition of DSP to the reaction mixture." (PMID 20957174, 2010).
sudden cardiac death (1 paper, 2024). "A mutation in the genes for lamin A/C (LMNA), desmoplakin (DSP) producing gene, sodium voltage-gated channel alpha subunit 5 (SCN5A) gene, and filamin C (FLNC) are genetic markers associated with DCMs that caused a higher risk in sudden cardiac death (SCD) related to malignant arrhythmias." (PMID 38975458, 2024).
Tachycardia (1 paper, 2025). A rapid heartrate that exceeds the range of the normal resting heartrate for age. "A separate colony of DSP-deficient mice via deletion of the Dsp gene had myocardial destruction and ventricular tachycardia in addition to cardiac myocyte adipogenesis, fibrogenesis, and apoptosis." (PMID 40725103, 2025).
viral myocarditis (1 paper, 2025). Myocarditis that is caused by an infection with a viral agent. "Loss of NFAT5 leads to desmoplakin downregulation and desmosomal disruption, which may underlie the cardiac dysfunction in viral myocarditis." (PMID 41156753, 2025).
tumor (60 papers, 2010 to 2026). "Other targets included Filaggrin-2, peroxiredoxin 6, Calmodulin-like protein 5, TBCEL-TECTA readthrough protein, Desmocollin 1 and 3, and Desmoplakin variant protein—with implications in diagnosis and tumour progression." (PMID 40725142, 2025). "In the pancreas of the mouse model, the loss of desmoplakin expression resulted in the disruption of desmosomal adhesions, that can promote increased local tumour invasion, independently of the adherens junction status." (PMID 39030443, 2024). "Reduced expression of DSP in a number of human primary tumours has been associated with tumour metastasis." (PMID 30566430, 2018). "The downregulation of DSP has been linked to tumor invasion." (PMID 40501071, 2025). "To define whether desmosomal genes are involved in the antitumor effects of SOX30, we focused on the most differentially expressed desmosomal genes associated with SOX30 and chose the three prominent tumor suppressors DSP, JUP and DSC3." (PMID 29855376, 2018). "In OSCC, the reduced expression of PKP1 caused a marked redistribution of DSP from the cell borders to diffuse cytoplasmic localization, resulting in decreased desmosome assembly and altered cell-cell adhesion, thereby increasing tumor cell motility and invasion." (PMID 34203070, 2021). "In AML, the interactions between GA in NPM1, KMT2A, and menin protein have been linked to leukemogenesis and represent new potential targets for anti-tumor therapies, including menin inhibitors (such as revumenib, ziftomenib, bleximenib, and DSP-5336)." (PMID 40867339, 2025). "An analysis of tumor-derived mRNA showed that combination of RT and DSP-0509 strongly increased the expression of anti-tumor effector molecules including Gzmb and Il12." (PMID 39054418, 2024). "Despite its inhibitory effects on Tregs in vitro, DSP-0509 leads to an increased number of Tregs within the tumor microenvironment." (PMID 39346737, 2024). "We also found that the combination of DSP-0509 with anti-CTLA-4 antibody resulted in increased effector memory T cells in the tumor." (PMID 36793737, 2023). "We confirmed that DSP-0509 enhanced the anti-tumor immune effects of anti-PD-1 antibody by inducing type I interferons via activation of dendritic cells and even CTLs." (PMID 36793737, 2023). "In our study, KRT13-overexpression led to decreased DSP and PG, reducing tumor suppressor functions in MCF7-KRT13 cells." (PMID 35078507, 2022). "After the nanoparticles were internalized by tumor cells, DSP and RNAse A were released from the pores of nanoparticles, and RNAse A degraded RNA, and activated DSP caused DNA damage, achieving the combination of chemotherapy and enzyme therapy." (PMID 35119544, 2022). "MIR4435-2HG can bind to DSP and inhibit DSP and its cascade reaction, thereby activating Wnt/β-catenin signal transduction, promoting tumor growth, metastasis, and EMT." (PMID 35784328, 2022). "DSP expression was highest in the centre of the tumours, where the most differentiated cells were found." (PMID 34001250, 2021). "Previous studies have shown that DSP protein dysregulation affects tumor behavior in various human cancers, including OSCC." (PMID 34203070, 2021). "Consistent with that, using an induced overexpressing DSP model of non-small cell lung cancer (NSCLC), the tumour-suppressive function of DSP behaviour was demonstrated through the inhibition of the Wnt/β-catenin/TCF/LEF (transcription factor) pathway." (PMID 34001250, 2021).
tumor (continued). "A tumor suppression study of DSP based on 4T1-Luc tumor-bearing BALB/C mice also exhibited a superior antitumor activity, lower cytotoxicity, and almost no hemotoxicity in vivo." (PMID 34452113, 2021). "The deletion of DSP induced tumor microinvasion in genetically modified mice, developing neuroendocrine pancreas cancer." (PMID 32498335, 2020). "In summary, we found that lncRNA UPLA1 was regulated by YY1 and promoted Wnt/β-catenin signalling by binding to DSP, thus leading to tumour progression in LUAD." (PMID 33221813, 2020). "DSP acts as a tumor suppressor by inhibiting the Wnt/β-catenin signaling in non-small cell lung cancer." (PMID 32498335, 2020). "Comparison of desmoplakin staining in HER2+/BL-ΔP and HER2+/BL-wt tumor specimens highlighted the presence of visible junctions with a punctate desmoplakin staining at cell-cell contacts in 87.5% of HER2+/BL-wt tumors." (PMID 31938048, 2020). "All of this shows desmoplakin’s role as a tumor suppressor, with potential implications for clinical applications." (PMID 29587367, 2018). "Similar to desmoplakin and its tumor suppressor characteristics, the overexpression of periplakin suppressed the proliferation of colon cancer cells and reduced the expression of pro-cell cycle regulators." (PMID 29373494, 2018). "Taken together, these experimental studies provide additional context to the role of desmoplakin as a tumor suppressor." (PMID 29373494, 2018). "Desmoplakin has been shown to be a tumor suppressor with decreased expression observed in several cancers." (PMID 29587367, 2018). "Since the desmosomal proteins play a major role in the process of tumour cell invasion, we analyzed the expression of major desmosomal proteins-desmoplakin, desmoglein and plakoglobin, in all the three OC models." (PMID 27501241, 2016). "The authors also expressed plakoglobin in the renal carcinoma cell line KTCTL 60, which lacks endogenous expression of E-cadherin and desmosomal cadherins, α-catenin, β-catenin, plakoglobin, and desmoplakin and induces tumor formation in mice." (PMID 22481945, 2012). "Both prostate specific genes (e.g., PSA/Kallikrein 3 and Kallikrein 2) and epithelial marker genes (e.g., keratin 18 and desmoplakin) were expressed in tumor epithelial cells." (PMID 20426842, 2010). "Although DSP is a known tumor suppressor, its expression level is regulated by DNA methylation." (PMID 41187747, 2025). "Whereas DSP can act as a tumour suppressor by inhibition of Wnt/β-catenin signalling." (PMID 39682273, 2024). "We have clarified that DSP-0509 decreased macrophage in Tumor." (PMID 39346737, 2024). "Besides maintaining the integrity of desmosomes, DSP also plays an important role as tumor suppressor by regulating various signaling pathways in cancer cells." (PMID 38952985, 2024). "Considering the lymph node and tumor analysis, we speculate that the combination of DSP-0509 with anti-PD-1 antibody induced central memory T cell in lymph node and differentiation from central memory T cell to effector memory T cell in tumor." (PMID 36793737, 2023). "Recent study has shown that MIR4435-2HG could promote tumor metastasis in GC via targeting Wnt/β-catenin and desmoplakin." (PMID 35794986, 2022). "However, the tumour suppressive role of DSP in cell context dependent and relies on the differentiation status of the tumour, as enhanced expression of DSP is observed in differentiated tumours." (PMID 34001250, 2021). "Previously we have shown that plakins (PPL, DSP, PLEC, EVPL) expressed in the ascites-derived tumour cells from patients with chemotherapy-treatment associated recurrence were significantly lower than plakins (PPL, DSP, EVPL, PLEC) in chemonaive ascites-derived tumour cells." (PMID 34001250, 2021).
tumor (continued). "When DSP/siRNA was uptaken into tumor cells, a high concentration of GSH in cytosol could degrade DSP NG into single PEI-1800 and dextrin with low toxicity followed by the controlled release of the packed siRNA." (PMID 34452113, 2021). "Consistent with our theory, the protein expression of MMP7 and CCND1 were downregulated in a SOX30-overexpressing cell line and xenograft tumors; MMP7 and CCND1 expression were increased significantly in SOX30-overexpressing cells, or tumor tissue after DSP or JUP expression was blocked." (PMID 29855376, 2018). "SJG15 cells, derived from a tumour that showed early recurrence and high metastatic potential, had the most disrupted micro-epidermal phenotype and key junctional proteins (E-ad P-cadherin and DSP) were displaced from the cell–cell interface." (PMID 22541538, 2012). "Our results demonstrate that loss of desmoplakin expression and resultant disruption of desmosomal adhesion can promote increased local tumor invasion independent of adherens junction status." (PMID 20862307, 2010). "Using genetically modified mice in pancreatic neuroendocrine tumours changes in DSP and other desmosomal protein expression is an early event in the tumourigenic process and preludes changes in the expression of adheren junction proteins and tumour cell invasion." (PMID 34001250, 2021). "Notably, UPLA1 could inhibit the tumour suppressor activity of DSP after binding to DSP and promote Wnt/β-catenin signalling." (PMID 33221813, 2020). "The mIHC images revealed that marker genes of epithelial cells (EPCAM, DSP and TXNRD1) were highly expressed in tumor regions, especially in the metastasis-related regions." (PMID 39741182, 2025). "GHRL, KLF4, and DUSP5 expression levels were relatively lower in tumor tissues, whereas DSP, PERP, and MMP9 were highly expressed in tumor tissues." (PMID 38273348, 2024). "Since monocytes are known to express the DSP-0509 target molecule TLR7, it is reasonable to attribute the strength of the anti-tumor activity of the combination with RT to strong DSP-0509-induced activation of monocytes via TLR7 signal upregulation." (PMID 39054418, 2024). "The results showed that the expression of ACACB, ATP8B4, C14orf28, CIRBP, and DTWD1 were higher in normal tissues, and the content of CDC6, DSP, HMGB3, HNRNPA3P1, PPP1R14C, and TPX2 were higher in tumor tissues." (PMID 35778922, 2022). "To evaluate whether DSP-0509 directly induce immunogenicity in tumor cells, we evaluated the expression of PD-L1 and H2Kd on CT26 cells in the presence of DSP-0509." (PMID 36793737, 2023). "DSP crosslinking did not appear to compromise the integrity of cellular RNA from our primary tumor sample, and the sequencing results were comparable to those obtained from unfixed samples." (PMID 36142141, 2022). "In a RIP1-Tag2 (RT2) mouse model of islet cell carcinogenesis, DSP has been shown to influence local tumour invasion, but it does not influence vast tumour invasion and metastasis." (PMID 36291586, 2022).
tumor (continued). "Desmoplakin (DSP), the first discovered member of the Plakin family of proteins and a significant component of desmosomal plaques, is considered to play an important role in the early stages of tumor development." (PMID 32754285, 2020). "To further investigate whether upregulation of DSP, JUP and DSC3 are necessary for SOX30-medicated tumorigenesis and metastasis in vivo, we utilized a xenograft tumor model using these stable cell lines." (PMID 29855376, 2018). "Genetic deletion of one of these desmosomal components, desmoplakin, resulted in increased local tumor invasion without affecting tumor growth parameters in RT2 PNETs." (PMID 20862307, 2010). "In this tumor analysis, DSP-0509 monotherapy did not increase Cd8a or Gzmb expression." (PMID 39054418, 2024). "DSP-0509 in these mice showed no clear tumor growth inhibitory activity." (PMID 36793737, 2023). "However, the downstream signaling pathway of these desmosomal genes in regulating tumor progression is not entirely clear, except for the three canonical tumor suppressor desmoplakin (DSP), junction plakoglobin (JUP) and desmocollin 3 (DSC3)." (PMID 29855376, 2018). "Furthermore, we stained for desmoplakin that, when absent, leads to more invasive tumor growth and is absent or reduced in many human epithelial cancers." (PMID 23536778, 2013). "Expression levels of the mesenchymal marker VIM (p = 0.02) were significantly higher in high BMI tumor samples, but levels of epithelial markers CDH (p = 0.32) or DSP (p = 0.13) were not significantly altered." (PMID 26424075, 2015). "The promoters of DSP, FZD8, KCNH2, and PPP1R14A were methylated in 28%, 67%, 22%, and 78% of the 36 tumor samples, respectively, but not in control samples." (PMID 24260260, 2013).